NFU1 (NFU1 iron-sulfur cluster scaffold)
Description:
Iron-sulfur cluster scaffold protein which can assemble [4Fe-4S] clusters and deliver them to target proteins.
Synonyms: HIRIP5; CGI-33; NifU; NIFUC; HIRIP; MMDFS; MMDS1; Nfu; SPG93
Tractability: PROTAC: its protein half-life has been measured.
Gene: Protein-coding gene on chromosome 2 (69,396,113 to 69,437,657, reverse strand). Ensembl gene ENSG00000169599.
Subcellular location: Mitochondrion; Cytoplasm, cytosol
Subcellular location (Human Protein Atlas): Cytosol; Nucleoplasm
Pathways (Reactome):
Metabolism of proteins: Protein lipoylation
Gene Ontology:
Molecular function: 2 iron, 2 sulfur cluster binding; 4 iron, 4 sulfur cluster binding; iron ion binding; protein binding; iron-sulfur cluster binding
Biological process: iron-sulfur cluster assembly; protein maturation
Cellular component: cytosol; mitochondrion; nucleus; mitochondrial matrix
Genetic constraint (gnomAD): Loss-of-function variants: 12 observed, 12.51 expected, observed/expected ratio (o/e) 0.96, 90% interval 0.61 to 1.54. The upper end of that interval is the gene's LOEUF score, 1.54, which puts it in group 6 of 6, group 1 being the genes least tolerant of losing a copy. Missense variants: 166 observed, 165.28 expected, observed/expected ratio (o/e) 1, 90% interval 0.88 to 1.14. Synonymous variants: 74 observed, 61.2 expected, observed/expected ratio (o/e) 1.21, 90% interval 1 to 1.47.
Gene-disease validity (ClinGen):
ClinGen rates the evidence that NFU1 causes each of these diseases.
mitochondrial disease (autosomal recessive): Definitive.
Homologues: Orthologues: chimpanzee NFU1 (94% identical), pig NFU1 (94% identical), macaque NFU1 (93% identical), rabbit NFU1 (92% identical), guinea pig NFU1 (91% identical), dog NFU1 (89% identical), mouse Nfu1 (88% identical), rat Nfu1 (88% identical), Drosophila melanogaster CG32500 (54% identical), Drosophila melanogaster CG32857 (54% identical), Drosophila melanogaster CG33502 (54% identical), Caenorhabditis elegans nfu-1 (46% identical).
Diseases named in the same sentence as NFU1 in open-access papers:
NFU1 is named in the same sentence as 37 diseases in open-access papers, as found by Europe PMC text mining. Sharing a sentence is not in itself a finding about the gene and the disease. The quoted sentences say what the papers report.
pulmonary hypertension (10 papers, 2013 to 2025). Increased pressure within the pulmonary circulation due to lung or heart disorder. "Individuals harboring pathogenic biallelic NFU1 variants present with early-onset failure to thrive, pulmonary hypertension, encephalopathy, and neurological regression." (PMID 35379322, 2022). "More recently, a loss-of-function mutation in NFU1 has been identified as another autosomal gene mutation that cause spontaneous development of pulmonary hypertension with higher penetrance in females." (PMID 34068984, 2021). "Reproduction of this NFU1 mutation in rats by CRISPR/Cas9 engineered gene modification caused spontaneous development of pulmonary hypertension with a greater female penetrance." (PMID 34068984, 2021). "We also recently showed that rats with a mutation in NFU1 protein develop pulmonary arterial hypertension with a remarkable demonstration of sexual dimorphism as found in humans." (PMID 32188512, 2020). "Assessment of mitochondria respiratory complexes showed a decrease in Complexes I, II and III activities in patients with the NFU1 mutation, thus, pointing on respiratory chain failure as an important contributor in the development of pulmonary hypertension." (PMID 29685148, 2018). "It was also reported that the mutations in the iron-sulfur chaperon protein NFU1 have a strong association with pulmonary hypertension development." (PMID 29685148, 2018). "All seven patients with NFU1 mutation developed fatal encephalopathy and pulmonary hypertension." (PMID 29685148, 2018). "Mutations in NFU1, required late in the maturation of Fe-S clusters, caused a syndrome of fatal infantile encephalopathy and/or pulmonary hypertension in Spanish and Mexican families with combined defects of PDHc, complex II, lipoic acid synthase and the glycine cleavage system." (PMID 24299452, 2013). "Iron deficiency is another feature that has been keenly observed in PH models, while findings regarding the role of NFU1 dysfunction related to mitochondrial dysfunction and pulmonary hypertension have been revealed elegantly in several studies." (PMID 36829931, 2023). "Although not necessarily persistent and only observed in 50% of cases, pulmonary hypertension in infancy might be an additional clinical feature to prioritize testing of NFU1 amongst several other candidate genes." (PMID 25918518, 2015).
multiple mitochondrial dysfunction syndrome (8 papers, 2014 to 2025). "The methodology we have adopted was based on Pubmed searches using “multiple mitochondrial dysfunction syndrome”, “NFU1”, “BOLA3”, “IBA57”, “ISCA2”, and “ISCA1” as keywords." (PMID 34440194, 2021). "Defects in several proteins involved in the biosynthesis and trafficking of [4Fe-4S] clusters are associated with multiple mitochondrial dysfunctions syndromes (MMDS), with NFU1 causing MMDS1, BOLA3 causing MMDS2, IBA57 causing MMDS3, ISCA2 causing MMDS4, and ISCA1 causing MMDS5." (PMID 32151725, 2020). "Genetic defects in NFU1 (causing MMDS1, OMIM #605711), BOLA3 (causing MMDS2, OMIM #614299), and IBA57 (causing MMDS3, OMIM #615330), all factors acting in the final step of the assembly of [4Fe–4S] proteins, have been designated multiple mitochondrial dysfunction syndromes (MMDSs)." (PMID 25918518, 2015).
multiple mitochondrial dysfunctions syndrome 1 (6 papers, 2018 to 2023). Any fatal multiple mitochondrial dysfunctions syndrome in which the cause of the disease is a mutation in the NFU1 gene. "Multiple mitochondrial dysfunctions syndrome 1 (MMDS1) is a rare autosomal-recessive disorder caused by mutations in the protein NFU1." (PMID 36645076, 2023). "Bi‐allelic variants in Iron–Sulfur Cluster Scaffold (NFU1) have previously been associated with multiple mitochondrial dysfunctions syndrome 1 (MMDS1) characterized by early‐onset rapidly fatal leukoencephalopathy." (PMID 36256512, 2022). "The function of NFU1 to deliver ISCs to its targets is of vital importance as variations altering the function of NFU1 are causative in the disease Multiple Mitochondrial Dysfunctions Syndrome 1 (MMDS1)." (PMID 34449775, 2021). "Mutations in NFU1 are associated with genetic diseases such as multiple mitochondrial dysfunctions syndrome 1 (MMDS1) that involve defects in mitochondrial [4Fe-4S] proteins." (PMID 32151725, 2020). "Clinical and genetic studies of patients of multiple mitochondrial dysfunctions syndromes 1 (MMDS1) identified mutations in the gene for NFU1." (PMID 30200358, 2018). "Multiple Mitochondrial Dysfunctions Syndrome 1 (MMDS1) is a rare, autosomal recessive disorder caused by mutations in the NFU1 gene." (PMID 34449775, 2021). "Dystonia is one of the most common symptoms of multiple mitochondrial dysfunctions syndrome 1 (MMDS1), a disease associated with mutations in the causative gene (NFU1) that impair iron–sulfur cluster biogenesis." (PMID 36645076, 2023). "In human, mutations in NFU1, BOLA3, IBA57, ISCA2, and ISCA1 genes lead to Multiple Mitochondrial Dysfunctions Syndromes 1 to 5 (MMDS1 to MMDS5) respectively." (PMID 35677241, 2022). "One such disease is Multiple Mitochondrial Dysfunctions Syndrome 1, a pediatric-fatal disease that is poorly understood in part due to the lack of clarity about how mutations in the causative gene, NFU1, affect protein function and phenotype development and severity." (PMID 34449775, 2021).
Encephalopathy (4 papers, 2015 to 2022). Encephalopathy is a term that means brain disease, damage, or malfunction. "Recently an early onset lethal encephalopathy has been described in relation to mutations of NFU1, one of the genes involved in iron-sulfur cluster metabolism." (PMID 25758857, 2015). "Bi-allelic pathogenic variants in the NFU1 gene cause MMDS type 1 (MMDS1, MIM#605711), clinically characterized by severe encephalopathy that manifests in the first year of life, with evidences of decreased energetic metabolism." (PMID 35883565, 2022).
Leukoencephalopathy (3 papers, 2015 to 2022). This term describes abnormality of the white matter of the cerebrum resulting from damage to the myelin sheaths of nerve cells. "Our case clearly suggests the importance of considering NFU1 mutation in slowly evolving leukoencephalopathy with high glycine concentration." (PMID 25758857, 2015).
acute kidney injury (2 papers, 2023 to 2025). Sudden and sustained deterioration of the kidney function characterized by decreased glomerular filtration rate, increased serum creatinine or oliguria. "The potential involvement of the p.M25K NFU1 variant in FHHNC renal failure progression is further supported by the fact that it is considered a common variant with a MAF of 0.40 according to the gnomAD browser." (PMID 40173198, 2025).
Infantile encephalopathy (2 papers, 2013 to 2016). Encephalopathy with onset in the infantile period. "The clinical phenotypes of patients with mutations in NFU1 or BOLA3 were similar with neurological regression, infantile encephalopathy and hyperglycinemia." (PMID 27532773, 2016).
Spastic paraparesis (2 papers, 2015 to 2025). Partial loss of the ability to move the lower limbs accompanied by spasticity of the lower limbs. "NFU1 deficiency, as reported in cases of spastic paraparesis, exacerbates mitochondrial vulnerability and can lead to acute worsening during infections, which connects to our findings of heightened immune-related pathway activation." (PMID 40051915, 2025). "We report a new NFU1 mutated patient presenting with a milder phenotype characterized by a later onset, a slowly progressive spastic paraparesis with relapsing-remitting episodes, mild cognitive impairment and a long survival." (PMID 25758857, 2015). "Specifically, disruptions were observed in mitochondrial dynamics and calcium homeostasis, alongside downregulation of key proteins like COX11, a copper chaperone for complex IV assembly, and NFU1, an iron-sulfur cluster protein linked to spastic paraparesis and infection-related worsening." (PMID 40051915, 2025).
colorectal cancer (1 paper, 2025). A primary or metastatic malignant neoplasm that affects the colon or rectum. "According to a genome-wide CRISPR-Cas9 cell viability screen under physiological and acidic conditions, some researchers have systematically identified the important NFU1 gene associated with pH-related fitness defects in colorectal cancer cells." (PMID 39991576, 2025).
glycogen storage diseases (1 paper, 2022).
Huntington disease (1 paper, 2017). Huntington disease (HD) is a rare neurodegenerative disorder of the central nervous system characterized by unwanted choreatic movements, behavioral and psychiatric disturbances and dementia. "NFU1 has also been recently implicated in Huntington's disease, supporting an association between iron homeostasis and proteostasis in neurological disorders." (PMID 28768697, 2017).
kidney cancer (1 paper, 2022). Primary or metastatic malignant neoplasm involving the kidney. "In our research, we found that NFU1, ISCA1, ISCA2, C1ORF69, and BLOA3 were altered significantly in kidney cancer tissues in multiple datasets." (PMID 36385109, 2022).
kidney failure (1 paper, 2025). An acute or chronic condition that is characterized by the inability of the kidneys to adequately filter the blood. "While we have identified promising potential modifier variants in NFU1, DMD, HPS5, CLDN8 and CLDN17, their functional impact on FHHNC progression towards kidney failure remains to be characterized." (PMID 40173198, 2025).
lactic acidosis (1 paper, 2014). Metabolic acidosis characterized by the accumulation of lactate in the body. "Since now three reports have described 14 patients belonging to 11 families with NFU1 mutations: most cases presented with infantile encephalopathy associate with pulmonary hypertension, lactic acidosis, hyperglycinemia and severe regression leading to death before the age 15 months." (PMID 25477904, 2014).
Leigh syndrome (1 paper, 2022). A progressive neurological disease defined by specific neuropathological features associating brainstem and basal ganglia lesions. "This case presents the first association of pathogenic NFU1 variants with Leigh syndrome, thus expanding the clinical phenotype." (PMID 35379322, 2022).
nephrolithiasis (1 paper, 2023). The presence of a calculus in the pelvis of the kidney; this is most often composed of mineral salts and proteins. "Among these, rs74637005 is located in the exonic region of NFU1, a gene previously shown to be associated with both calcium levels and elevation in metabolic biomarkers and rs17438465 is located between EVX1 and HIBADH, genes that have been associated with nephrolithiasis and cardiovascular disease." (PMID 37124606, 2023).
portal hypertension (1 paper, 2020). Increased blood pressure in the portal venous system. "Although PH can be caused by chronic liver disease and portal hypertension, PH after LT is infrequent; PH has also been reported in patients with primary mitochondrial diseases (e.g. m.3243A > G, NFU1, BOLA3), however, the mechanism underlying this remains unknown." (PMID 32703289, 2020).
renal clear cell carcinoma (1 paper, 2022). "More importantly, the results of immunohistochemistry showed that the expression of NFU1, ISCA1, ISCA2 and C1ORF69 in normal tissues was higher than that in renal clear cell carcinoma tissues." (PMID 36385109, 2022). "The results of immunohistochemistry showed that the expression levels of NFU1, ISCA1, ISCA2 and C1ORF69 in normal tissues were higher than those in renal clear cell carcinoma tissues, which further verified our previous hypotheses." (PMID 36385109, 2022).
von Hippel-Lindau disease (1 paper, 2022). An autosomal dominant disorder caused by pathogenic variants in the VHL gene, leading to an increased risk of various benign and malignant tumors, including hemangioblastomas, retinal hemangiomas, endolymphatic sac tumors, renal cell carcinoma, and pheochromocytomas.
cancer (4 papers, 2021 to 2025). A tumor composed of atypical neoplastic, often pleomorphic cells that invade other tissues. "Through multi-omics and pan-cancer analyses, CARS2, NFU1, and SYNJ1 were identified as hub genes to construct LRGS and regulate the lactate-related TME in HNSCC." (PMID 39991576, 2025). "Targeting genes such as NDUFS1, NFU1, or IBA57 is therefore a potential route for selectively killing cancer cells in acidic microenvironments." (PMID 35263578, 2022). "There were significant differences in the mRNA expression levels of ISCA1, ISCA2, C1ORF69 and NFU1 in KIRC among different tumor grades and individual cancer stages." (PMID 36385109, 2022). "Downregulation of proteins involved in the mitochondrial respiratory chain like NFU1, ACO2, PDHA1, and proteins like DECR1, CNDP2, and SPINT1, which have a tumor suppressive role in different cancers were noted." (PMID 34885041, 2021). "Moreover, there were significant differences in the mRNA expression levels of ISCA1, ISCA2, C1ORF69 and NFU1 in KIRC among different tumor grades and individual cancer stages." (PMID 36385109, 2022). "The results showed that the expression levels of ISCA1, ISCA2, C1ORF69 and NFU1 were significantly different in normal tissues versus KIRC tumor tissues (p < 0.01), among different tumor grades (p < 0.01), and among different individual cancer stages (p < 0.01)." (PMID 36385109, 2022).
mitochondrial disease (3 papers, 2018 to 2022). "A Gly to Cys substitution in Nfu1, a mitochondrial protein involved in FeS cluster assembly that also carries a CxxC motif, causes a dominant genetic effect in yeast and severe mitochondrial disease in humans." (PMID 29982452, 2018).
genetic diseases (2 papers, 2016 to 2020). "Mutations in NFU1 and BOLA3 have been linked to genetic diseases with defects in mitochondrial Fe-S centers." (PMID 27532773, 2016). "For example, a study on patients with a rare human genetic disease suggested that proteins called BOLA3 and NFU1 might also play a role in this process." (PMID 27532773, 2016).
tumor (2 papers, 2021 to 2022). "We evaluated the expression differences of ISCA1, ISCA2, C1ORF69 and NFU1 normal tissues versus tumor tissues and among tumor tissues of KIRC." (PMID 36385109, 2022). "In addition, we also analyzed the expression of NFU1, ISCA1, ISCA2, C1ORF69 and BLOA3 genes in various tumor types through the oncomine database." (PMID 36385109, 2022).
kidney disease (1 paper, 2025). "Renal involvement has been also described for MMDS patients harbouring mutations in BOLA3, a protein that cooperates with NFU1 in the last steps of maturation and transfer of [4Fe‐4S] clusters into target proteins, further supporting the role of [Fe‐S] cluster assembly defects on kidney disease." (PMID 40173198, 2025).
NFU1 also shares sentences with these, for which no sentence is quoted: Dystonia (2 papers); cardiovascular disease (1); Cognitive impairment (1); disc degeneration (1); Failure to thrive (1); hereditary spastic paraplegia (1); infection (1); leukodystrophy (1); Neurodevelopmental delay (1); neurodevelopmental disorder (1); neurological disorders (1); renal failure (1); Salmonella Infections (1).